CD27 (CD27 molecule)
Diseases named in the same sentence as CD27 in open-access papers (continued):
Sharing a sentence is not in itself a finding about the gene and the disease.
Hepatitis (3 papers, 2021 to 2024). Inflammation of the liver. "To illustrate the potential utility of restricted biomarkers, we compared the performance of CD27+ CD28+ CD4+ TEM frequency as a biomarker of hepatitis risk in our unrestricted and restricted datasets." (PMID 38926389, 2024). "Using our restriction method, we identified CD27+ CD28+ CD4+ TEM cell frequency relative to CD4+ in blood as a biomarker of hepatitis risk after dataset restriction." (PMID 38926389, 2024). "Accordingly, using the unrestricted dataset, CD27+ CD28+ CD4+ TEM (%) correctly predicted the incidence of hepatitis in 74 of 110 patients." (PMID 38926389, 2024). "Of note, also the HBvac NR who was the only individual without protective anti-HBs titer even after booster with third-generation hepatitis B vaccine had very low frequencies of IL-10 expressing CD24+CD27+ and CD24highCD38high Breg and B10+ cells." (PMID 34566969, 2021). "In univariate analyses, dataset restriction identified new biomarkers associated with ICI-related hepatitis, including CD27+ CD28+ CD4+ TEM cells, that were not returned by conventional methods." (PMID 38926389, 2024). "The discriminatory cutoff for patient classification, defined by the Youden index, was the same for both the restricted and unrestricted datasets, such that samples with more than 9.56% of CD27+ CD28+ CD4+ TEM relative to CD4+ are predicted to be hepatitis positive." (PMID 38926389, 2024). "We performed comparative phenotypic and frequency analysis of Breg subsets (CD24+CD27+ and CD24highCD38high Breg) in second-generation hepatitis B vaccine non-responders (2nd HBvac NR, n = 11) and responders (2nd HBvac R, n = 8) before (d0), on day 7 (d7), and 28 (d28) after booster vaccination." (PMID 34566969, 2021). "Interestingly we did not observe decreased numbers of CD24+CD27+ and CD24highCD38high Breg post-boost with the second-generation hepatitis B vaccine." (PMID 34566969, 2021).
hepatitis B (3 papers, 2017 to 2024). "Previous findings showed that among healthy adults vaccinated against hepatitis B, the proportions of CD24+CD27+Breg and CD24+CD38high Breg cells were significantly lower in the anti-HBs-positive group than in the anti-HBs-negative group." (PMID 38555445, 2024).
liver cirrhosis (3 papers, 2020 to 2022). "Remarkably, we indicated increased percentage of hepatic atMBC and CD27+CD38++plasma cells in ACLF, which was in sharp contrast to liver cirrhosis and HCs." (PMID 36505417, 2022). "An exceptional expression was observed for the co-stimulatory molecule CD27, which was expressed at significantly lower levels on CD4+ T cells of patients with compensated and acutely decompensated liver cirrhosis." (PMID 33574809, 2020). "Although the CD27+ memory B cells are significantly depleted, liver cirrhosis does not promote the expansion of CD11c+Tbet+ aMBCs but significantly increases the naïve B cell and Trans&GC B cell populations." (PMID 33099582, 2020).
liver disease (3 papers, 2024 to 2025). "During liver disease progression, spatial transcriptomics and multiplex immunofluorescence show the aggregation of CD27+ memory B cells and plasma cells in the portal tract of PBC patients." (PMID 41202080, 2025). "IgM and IgD molecules were further detected on CD19+B220+CD5+CD27+ NSw MBCs and CD19+B220+CD138+ PBs in murine liver disease." (PMID 39611128, 2024). "Additionally, two other B cell subsets (CD27+IgD+ NSw MBCs and CD19+B220+CD138+ PBs) were found in MASLD and HCC tissues, which might also play a protumorigenic role in liver disease progression." (PMID 39611128, 2024).
liver fibrosis (3 papers, 2023 to 2024). "Adoptive transfer of CD27+CD11b+ double-positive NK cells attenuated CCl4-induced liver fibrosis in mice." (PMID 38307876, 2024). "In the PB of HCV+ patients with advanced liver fibrosis, there was a lower proportion of CD62L+; CD62L+/CD94++; CD27+; CD127+/CD27+ and CXCR3+/CD27+ NK subsets, as compared to patients with mild/moderate liver fibrosis." (PMID 37443584, 2023).
metastatic melanoma (3 papers, 2020 to 2025). A melanoma that has spread from its primary site to another anatomic site. "The number of transferred CD8+CD27+ T cells has previously been associated with an improved patient response to the adoptive therapy treatment using autologous TILs for metastatic melanoma." (PMID 33208551, 2020). "In this study, we evidenced increased levels of soluble CD27 in the plasma of patients with metastatic melanoma across two patient cohorts." (PMID 40148586, 2025). "As previously documented in the literature, our mIF analysis revealed that metastatic melanoma patients express CD70 and are significantly infiltrated by CD27+T lymphocytes." (PMID 40148586, 2025). "Previous findings from our group showed a positive correlation between the levels of interaction between CD27 and CD70 in the TME and sCD27 concentrations in plasma, prompting us to measure these concentrations in patients with metastatic melanoma." (PMID 40148586, 2025).
myocardial infarction (3 papers, 2019 to 2022). Gross necrosis of the myocardium, as a result of interruption of the blood supply to the area, as in coronary thrombosis. "CD45RA and CD27 co-expression was analyzed on peripheral lymphocytes and the percentages of naïve T cells (CD45RA+ CD27+) and effector/memory T cells (CD45RA–CD27–) were compared before and 1 h after myocardial infarction." (PMID 30898123, 2019).
neuroblastoma (3 papers, 2018 to 2025). Neuroblastoma (NB) is the most common solid, extracranial childhood tumor. "Clinically, treatment with a GD2-targeting CD27/CD28 CAR-T cells yielded 15% PR and 38% SD in 34 neuroblastoma patients, with a one-year survival rate of 74% (NCT02992210 and NCT02765243)." (PMID 35053463, 2022).
neuromyelitis optica spectrum disorder (3 papers, 2023 to 2024). "BCDT reinfusion based on CD27+ memory B-cells has been adopted by certain groups treating patients with neuromyelitis optica spectrum disorder, myasthenia gravis, as well as patients with MS." (PMID 37882961, 2023).
Parkinson disease (3 papers, 2021 to 2022). A progressive degenerative disorder of the central nervous system characterized by loss of dopamine producing neurons in the substantia nigra and the presence of Lewy bodies in the substantia nigra and locus coeruleus. "We found that PD patients exhibited decreased naïve CD8+ T cells (CD3+ CD8+ CD45RA+ CD45RO−) and increased late-differentiated CD4+ T cells (CD3+ CD4+ CD28− CD27−), compared to HC, which were not affected by anti-parkinsonism medication administration." (PMID 35608657, 2022). "However, the TEMRA population was defined differently (CD8+CD45RA+CD27−, as opposed to CD8+CD45RA+CCR7−); furthermore, T cell immunosenescence may play differing roles in Alzheimer’s and Parkinson’s diseases." (PMID 34645462, 2021).
pemphigus (3 papers, 2019 to 2020). Pemphigus is a group of rare autoimmune diseases that cause blistering of the skin and mucous membranes (mouth, nose, throat, eyes, and genitals).This conditioncan occur at any age, but often strikes people in middle or older age. "Relative to patients with active pemphigus, those experiencing complete remission following rituximab displayed under-expression of IL-1β and the CD27 memory marker genes." (PMID 33505392, 2020).
prostate carcinoma (3 papers, 2021 to 2025). A carcinoma that arises from epithelial cells of the prostate gland. "Using C4-2B prostate cancer cells expressing PSCA, we next tested the cytotoxic activity of the 8t28Z CAR in comparison to two variations where the costimulatory domain was replaced with either a CD27- or 4-1BB–derived moiety (8t27Z and 8tBBZ, respectively)." (PMID 37134157, 2023).
psoriatic arthritis (3 papers, 2018 to 2026). Joint inflammation associated with psoriasis. "Expression levels of chemokine receptors from the CC and CXC family, as well as CD27, were assessed by flow cytometry in CD20+ mononuclear cells isolated from the peripheral blood (PB) and synovial fluid (SF) of RA and psoriatic arthritis patients." (PMID 29880013, 2018). "The increase in CD27 and OX40 expression across both subsets indicates chronic antigen experience, while the selective rise in 2B4 and KLRG1 within γδT cells in psoriatic arthritis is compatible with repeated stimulation and effector skewing described for chronically engaged γδT populations." (PMID 41596369, 2026).
pulmonary fibrosis (3 papers, 2018 to 2025). Chronic progressive interstitial lung disorder characterized by the replacement of the lung tissue by connective tissue, leading to progressive dyspnea, respiratory failure, or right heart failure. "Clinically, the expressions of CD27 and ICOS are enriched in CD8+ T cells within the lung tissues of patients with pulmonary fibrosis." (PMID 41262009, 2025). "Concentrations of CD38+ memory CD27− B-cells, IgA+ memory CD27+ B-cells, and IgM+ and IgD+ B-cells were significantly higher in patients affected with either FPF or HPS pulmonary fibrosis compared with unaffected controls." (PMID 29445374, 2018). "Moreover, It has been shown that up-regulation of CD27 activity on human T cells precisely activate CD70 activity on fibroblasts to reduce collagen deposition and inhibit pulmonary fibrosis by reducing fibroblast proliferation." (PMID 40433386, 2025). "Percentages of CD38+ memory CD27− B-cells, IgA+ memory CD27+ B-cells, IgM+ and IgD+ B-cells, and CD39+ T helper cells were significantly higher whereas CD39− T helper cells were significantly lower in patients with either FPF or HPS pulmonary fibrosis compared with URels." (PMID 29445374, 2018).
sarcoma (3 papers, 2015 to 2025). A usually aggressive malignant neoplasm of the soft tissue or bone. "In the B-cell compartment, an increase in class-switched memory B-cells (CD27 + IgM-IgD-) was seen in sarcoma patients vs. HV (115 vs. 5 % respectively; p = 0.02)." (PMID 26286851, 2015). "In our CLL cohort, CD5+CD19+CD27+ cells represented the discriminant phenotypic features of IL10+vs- and TGFβ1+vs- subsets, which also resembled CD19+CD81+CD27+CD25+PD-L1hi tumor evoked Bregs producing both IL10 and TGFβ1 in sarcomas." (PMID 36973425, 2023).
Splenomegaly (3 papers, 2014 to 2025). Abnormal increased size of the spleen. "Multiple studies, including those by Warnatz, Piqueras, and the EUROclass group, consistently demonstrated that a marked reduction in switched memory B cells (CD27+IgM−IgD−) in CVID patients is associated with immune dysregulation features such as splenomegaly, lymphadenopathy, and AICs." (PMID 40993545, 2025).
systemic sclerosis (3 papers, 2022). A chronic disorder, possibly autoimmune, marked by excessive production of collagen which results in hardening and thickening of body tissues. "CD27 expression was significantly elevated in the lesional skin and serum of patients with systemic sclerosis, with a significant association with disease severity." (PMID 35300124, 2022).
allergic asthma (2 papers, 2024). A asthma with a basis in a pathological type I hypersensitivity reaction. "Our study found that CD27+CD38+ plasmablasts and CD24hiCD38hi transitional B cells increased and were correlated with serum total IgE level, CD27− naive B cells and CD24hiCD27+ B cells decreased in children with allergic asthma." (PMID 38424520, 2024). "We found increased CD19+ B cells, CD27+ memory B cells and CD27+CD38+ plasmablasts while decreased CD27− naïve B cells in children with allergic asthma." (PMID 38424520, 2024). "As expected, the frequency of CD27+CD38+ plasmablasts, CD24hiCD38hi transitional B cells, CXCR5− Tph, CXCR5−ICOS+PD-1+ Tph, Tph2 subtypes and Tfh2 subtypes were weak positively correlated with serum total IgE level in children with allergic asthma." (PMID 38424520, 2024).
ankylosing spondylitis (2 papers, 2014 to 2021). An autoimmune chronic inflammatory disorder characterized by inflammation in the vertebral joints of the spine and sacroiliac joints. "Continuous measures of diseases activity, such as Bath Ankylosing Spondylitis Disease Activity Index (BASDAI), ASDAS and CRP as well as symptom duration were not correlated with increased frequencies of CD27-CD38lowCD21low B-cells." (PMID 34168654, 2021).
Anxiety (2 papers, 2021 to 2022). Intense feelings of nervousness, tension, or panic often arise in response to interpersonal stresses. "Meanwhile, CD4+CD27+CD28+ Th and Treg cells were significantly reduced in SLE patients with anxiety." (PMID 34955935, 2021). "Our findings indicated that the T cell subsets closely related to SLE (CD27+CD28+ Th/Treg, CD27−CD28− Th/Treg, CD45RA−CD27− Th, and CD45RA+HLADR+ Th) may be involved in SLE patients with anxiety." (PMID 34955935, 2021).
B cell deficiency (2 papers, 2019 to 2024). A broad classification of disorders where circulating numbers of B lymphocytes are decreased or ineffective. "In particular, active cGVHD correlated with a low proportion of CD19+CD27+ memory B-cells, confirming memory B-cell deficiency as a risk factor/marker for persistence of cGVHD." (PMID 31507582, 2019). "Moreover, CD19+CD27+ memory B cells in vitro basal cell death and B-cell deficiency degree clustered in PC1 (with ROS production and mitochondrial function) with high significant loading values (0.827 and 0.614, respectively)." (PMID 38596676, 2024). "Interestingly, the PCA in CD19+CD27+ memory B cells demonstrated a well-defined negative correlation between ROS production and either the in vitro basal cell death or the B-cell deficiency degree, given the nearly 180° angle that they formed." (PMID 38596676, 2024).
bladder cancer (2 papers, 2021 to 2024). "Therefore, our study aimed to investigate the role of tumor-specific T cells in bladder cancer immunotherapy by constructing TstcSig, consisting of five tumor-specific T cell-related genes: CD27, CACYBP, TIGIT, LCK, and VAMP5." (PMID 39033098, 2024). "We developed a five-gene signature (including VAMP5, TIGIT, LCK, CD27 and CACYBP) based on tumor-specific T cell-related genes to predict the immunotherapy response in bladder cancer patients." (PMID 39033098, 2024). "In conclusion, we have developed and validated a novel tumor-specific T cell signature (including VAMP5, TIGIT, LCK, CD27, and CACYBP) as a prognostic biomarker for bladder cancer patients treated with immunotherapy using single cell multi-omics data." (PMID 39033098, 2024). "Furthermore, Kaplan-Meier survival analysis revealed that the higher expression of VAMP5, TIGIT, LCK, CHORDC1, CD27, and CACYBP was correlated with better outcomes in bladder cancer patients treated with immunotherapy." (PMID 39033098, 2024).
bladder urothelial carcinoma (2 papers, 2023 to 2025). "Plasma from muscle-invasive, urothelial bladder cancer patients displayed higher levels of MMP7 (p = 0.028) and CCL23 (p = 0.03) compared to NMIBC patients, whereas urine displayed higher levels of CD27 (p = 0.044) and CD40 (p = 0.04) in the NMIBC group by two-sided Wilcoxon rank-sum tests." (PMID 37391708, 2023).
cardiomyopathy (2 papers, 2014 to 2021). A disease of the heart muscle or myocardium proper. "The innate-like B10 cells expansion observed in patients with cardiomyopathy would be associated with CD27− B10 cell subsets, while no predominant phenotype was found in the other groups." (PMID 34458163, 2021). "Furthermore, the most substantial differences were found in the augmentation of CD24+CD27+ in G0 and NI, together with a drop in the frequency of and CD27−CD38+ B cells in CCD patients with cardiomyopathy." (PMID 34458163, 2021). "Isolated B cells from CCD patients with or without cardiomyopathy and non-infected (NI) donors were stimulated with T. cruzi lysate or CpG + CD40L, and characterized by flow cytometry based on the expression of CD24, CD27, CD38, and the regulatory molecules IL-10 and PD-L1." (PMID 34458163, 2021).
Chagas disease (2 papers, 2014 to 2024). A parasitic infection caused by Trypanosoma cruzi. "We observed an increase in the frequency of effector CD27-, TRM, and EM cells with the progression of Chagas disease (groups A, B1, and B2/C/D) compared to CTL." (PMID 38726014, 2024). "Herein, we report that antigen-experienced (CD45RO+) T cells with a low degree of differentiation (CD27+/CD57−), a Th1 profile (Tbet+) and proliferative capacity (Ki67+) are recruited into the heart of patients with chronic advanced Chagas disease myocarditis." (PMID 25144227, 2014). "Higher levels of infiltrating cells with low degree of differentiation (i.e. CD27− expressing cells), lower T-bet expression and lower proliferative capacity were observed in GCM compared with severe Chagas disease myocarditis." (PMID 25144227, 2014).
chronic hepatitis C (2 papers, 2021 to 2025). "Reports showing the increased expression of CXCR3+ on CD27+ B cells in chronic hepatitis C support a model where these B cells could bind HCV and trans-infect permissive hepatocytes in the liver." (PMID 34975862, 2021).
CNS lymphoma (2 papers, 2021 to 2022). "Therefore, we propose that CD27 and CD38 should be incorporated into staining protocols for the detection of primary CNS lymphoma." (PMID 36153593, 2022).
diffuse large B-cell lymphoma (2 papers, 2022 to 2023). "In patients with diffuse large B-cell lymphoma (DLBCL), the loss of CD27 and CD28 expression in T cells correlates with the number of prior chemotherapy cycles." (PMID 38136380, 2023).
dysgammaglobulinemia (2 papers, 2018 to 2025). An immunologic deficiency state characterized by selective deficiencies of one or more, but not all, classes of immunoglobulins. "This may be related to the hypogammaglobulinemia and/or dysgammaglobulinemia associated with low number of CD27+ memory B cells that are frequently observed in these defects." (PMID 29942301, 2018). "Intrinsic defects in B cell development and function may also contribute directly to the hypo/dysgammaglobulinemia, like in RASGRP1, CTPS1, CD27 deficiencies, for which there is clear evidence that these genes are directly involved in B-cell development and/or function." (PMID 29942301, 2018). "Based on these immunological features, our screening strategy defined major criteria as dysgammaglobulinemia, decreased CD19+ B cells/decreased CD19+CD27+IgM-IgD- cells, an inverted CD4+/CD8+ T cell ratio, and increased CD8+CD45RA+CD27+ cells." (PMID 41583441, 2025).
experimental autoimmune encephalomyelitis (2 papers, 2017 to 2025). An autoimmune demyelinating disease of the central nervous system that is produced experimentally in animals by the injection of homogenized brain or spinal cord in Freund's adjuvant. "Using a mouse model of experimental autoimmune encephalomyelitis (EAE), the authors identified two distinct Th17 subsets: a stem-like CD27+ TCF1hi subset with lower anabolic metabolism and a CD27‒ T-bethi subset with higher metabolic activity that promotes transdifferentiation into Th1-like cells." (PMID 40634636, 2025).
gingivitis (2 papers, 2018 to 2024). A disorder involving inflammation of the gums; may affect surrounding and supporting structures of the teeth. "However, they found that memory B cells (CD19+CD27+CD38-) represented the majority in the B cell population in clinically healthy gingiva and in gingivitis tissues (around 90% of the B cell population)." (PMID 29447240, 2018).
hypothyroidism (2 papers, 2025). Abnormally low levels of thyroid hormone. "In hypothyroidism, HLA-DQA1 maintained high diagnostic accuracy with an AUC of 0.924, whereas CD27, though more moderate, still achieved an AUC of 0.664." (PMID 41202080, 2025). "In conclusion, our findings support an association between hypothyroidism and IPF risk, with observed alterations in the immune environment, particularly involving CD19 on IgD− CD27− cells and HVEM on T cells, which may play a mediating role." (PMID 40635577, 2025).